EGR3 (early growth response 3)
Diseases named in the same sentence as EGR3 in open-access papers (continued):
Sharing a sentence is not in itself a finding about the gene and the disease.
Myocardial fibrosis (4 papers, 2021 to 2025). "This regulatory axis (tsr007330/NAT10/EGR3) reveals a new mechanism for tsRNA regulation in myocardial fibrosis after MI, providing a new direction for targeted intervention." (PMID 40918194, 2025). "Second, researchers can further elucidate the molecular details of miR‐27a‐5p's mechanism of action to determine how the miR‐27a‐5p/Egr3 axis affects CF‐mediated myocardial fibrosis and the significance of the Tgf‐β cascade in this biological process." (PMID 33215816, 2021). "tsRNAs (rno-tsr007330) modulates myocardial fibrosis via NAT10-mediated EGR3 mRNA acetylation." (PMID 40565315, 2025). "Cardiac fibroblast miR-27a-5p may function as an inhibitor of pathological myocardial fibrosis and hypertrophy by negatively regulating Egr3 expression." (PMID 34233591, 2021). "The tsRNA tsr007330 is significantly downregulated after MI, and by antagonizing N-acetyltransferase NAT10, it inhibits the ac4C modification of early growth response protein 3 (EGR3) mRNA mediated by NAT10, thereby reducing myocardial fibrosis and improving cardiac function." (PMID 40918194, 2025).
non-small cell lung carcinoma (4 papers, 2020 to 2025). A group of at least three distinct histological types of lung cancer, including non-small cell squamous cell carcinoma, adenocarcinoma, and large cell carcinoma. "KSRP has been studied to suppress cell invasion and metastasis in non-small-cell lung cancer by regulating EGR3 mRNA degradation through miR-23a." (PMID 40699755, 2025). "KHSRP inhibits the invasion and migration of non-small cell lung cancer through the miR-23a/EGR3 axis." (PMID 39439895, 2024). "Moreover, KSRP was reported to attenuate invasive and metastatic features in non-small cell lung cancer (NSCLC) by negatively regulating oncogenic EGR3 mRNA stability through promoting the maturation of miR-23a, which targets EGR3 mRNA87." (PMID 38689093, 2024).
asthma (3 papers, 2023 to 2024). "The study demonstrated that EGR3 was increased in the serum of patients with asthma and PDGF‐BB‐induced HASMCs and was negatively regulated by miR‐7‐5p." (PMID 37102654, 2023). "The results displayed that the expression of EGR3 was prominently higher in patients with asthma than in healthy volunteers." (PMID 37102654, 2023). "This study is the first to elucidate the roles and potential mechanisms of lncRNA ANRIL in airway remodeling and to explore the relationship between lncRNA ANRIL, miR‐7‐5p, and EGR3 in asthma." (PMID 37102654, 2023). "Prior research has found that patients with asthma show high expression levels of FosB and Egr3." (PMID 38666929, 2024). "In addition, EGR3 was reported to be overexpressed in the lung of asthma patients and regulates the expression of IL-2, IL-6, and IL-8." (PMID 36979655, 2023).
glioma (3 papers, 2020 to 2025). A benign or malignant brain and spinal cord tumor that arises from glial cells (astrocytes, oligodendrocytes, ependymal cells). "Based on this, we hypothesized that EGR1 and EGR3 may be associated with tumour progression, possibly mediated through promotion of tumour cell migration, and thus hold prognostic value in gliomas." (PMID 32518380, 2020). "Prior pan-cancer analyses noted EGR3’s tumor-suppressive effects in gliomas but oncogenic functions in lung adenocarcinoma." (PMID 41472745, 2025). "A deeper understanding of the conflicting roles of EGR3 in gliomas requires careful consideration of the molecular context in which EGR3 operates." (PMID 40649712, 2025). "Although MYC and CDK1 were prioritized based on their consistent upregulation and well-established roles in glioma biology, it is likely that EGR3 governs a wider transcriptional network influencing multiple aspects of tumor progression." (PMID 40649712, 2025). "EGR3 protein expression was also found in all 207 gliomas with positive cell fractions varying from 5–95%." (PMID 32518380, 2020). "Previous studies have reported contradictory findings regarding EGR3′s function in gliomas." (PMID 40649712, 2025). "A clearer understanding of EGR3 may reconcile existing inconsistencies and clarify whether it contributes to glioma proliferation, migration, or therapeutic resistance." (PMID 40649712, 2025). "Differences in glioma subtypes, such as classical versus mesenchymal, may result in divergent transcriptional programs and responsiveness to EGR3." (PMID 40649712, 2025).
liver cancer (3 papers, 2020 to 2025). An epithelial or non-epithelial malignant neoplasm that arises from the liver. "MiRNA-210 and its target EGR3 may be potential therapeutic targets for HBV-associated liver cancer." (PMID 32138690, 2020). "In nasopharyngeal and liver cancer, oncogenic microRNAs, such as miR-483-5p and miR-210, directly target EGR3 to promote tumor progression and metastasis." (PMID 40649712, 2025). "EGR3 was a target of miRNA-210, which was down-regulated in the liver tissues of HBV-associated cirrhosis and liver cancer, and in HepG2 and HepG2.2.15 cells (P < 0.05)." (PMID 32138690, 2020). "The expression of EGR3 was down-regulated in the liver tissues of HBV-associated cirrhosis and liver cancer, which was contrary to miRNA-210." (PMID 32138690, 2020). "Silencing of miRNA-210 inhibits the progression of liver cancer and HBV-associated liver cancer via up-regulating EGR3." (PMID 32138690, 2020). "Note worthily, the abnormal expression of EGR3 is also observed in liver cancer." (PMID 32138690, 2020). "The mRNA and protein expression of EGR3 were significantly lower in liver tissues of the Cirrhosis group than in tissues of the Control group (P < 0.05), and were significantly lower in liver tissues of the Liver cancer group than in tissues of the Cirrhosis group (P < 0.05)." (PMID 32138690, 2020).
lung carcinoma (3 papers, 2021). "Considering the role of EGR3 in inflammation-associated diseases and in lung cancer we hypothesized that EGR3 exerts a significant effect in COPD." (PMID 34243729, 2021). "EGR3 acts as an oncogene in lung cancer, and COPD has been indicated to worsen lung cancer prognosis." (PMID 34243729, 2021). "The expressions of EGR1 and EGR3 in 20 different types of human cancers were downregulated compared with that in normal tissues, including BRCA, lung cancer, and ovarian cancer." (PMID 34178038, 2021).
lupus (3 papers, 2018 to 2024). "EGRs play an important role in the development of systemic autoimmune diseases, and the deficiency of EGR2 and EGR3, in particular, are related to the development of chronic inflammatory diseases, such as lupus, in murine models." (PMID 30319432, 2018). "Previously, EGR3 was indicated to exert vital roles in coronary heart disease and systemic lupus erythematosus." (PMID 34243729, 2021). "However, a much larger set of TFs contained in the TNF-α signaling gene set appeared among the active TFs in lupus cells; these include FOSL1, KLF6, RELB, BHLHE40, EGR3, and SMAD3." (PMID 39688922, 2024).
nasopharyngeal carcinoma (3 papers, 2021 to 2025). A carcinoma arising from the nasopharyngeal epithelium. "In nasopharyngeal carcinoma, EGR3 is activated under hypoxia and contributes to immunosuppression and tumor growth through regulation of IL10 and TGFB1 in regulatory B cells." (PMID 40649712, 2025).
psoriasis (3 papers, 2020 to 2021). An autoimmune condition characterized by red, well-delineated plaques with silvery scales that are usually on the extensor surfaces and scalp. "Several psoriasis-related genes were among the associated genes of hsa_skin_088763, including GATA6, SIK2, IL17RD, EGR3, FAS, LRIG1, and PPARGC1A." (PMID 34068434, 2021). "Among the associated genes were EGR3, GATA6, GATA3, and FOXN3, which play important roles in psoriasis." (PMID 34068434, 2021).
psychosis (3 papers, 2016 to 2018). "Since EGR3 functions as a transcription factor, we hypothesized that the downstream target genes regulated by EGR3 may also influence risk for psychotic disorders." (PMID 29867393, 2018). "However, studies in EGR3-deficient mice demonstrating psychosis-like phenotypes and hyperactivity that can be reversed with antipsychotic medications that are used in treatment of BD already provide important support for our findings." (PMID 27163206, 2016). "Moreover, rodent studies suggest that Egr-3 may underlie some of the effects of clozapine in treating both psychosis and bipolar symptoms, suggesting that further study of Egr-3 may yield critical insights into the etiology of mood disorders." (PMID 28503137, 2017). "In support of this hypothesis, our prior work has shown that Egr3-/- mice display behavioral abnormalities consistent with animal models of psychotic disorders that can be reversed by administration of medications used to treat these illnesses in humans." (PMID 29867393, 2018).
scoliosis (3 papers, 2010 to 2024). A congenital or acquired spinal deformity characterized by lateral curvature of the spine. "Interestingly, EGR3-deficient mice exhibit several neuromuscular defects including gait ataxia and scoliosis, symptoms which resemble those exhibited by Friedreich ataxia patients." (PMID 20808827, 2010). "Mice with a genetic mutation that results in a deficiency in transcription factor EGR3, responsible for the formation of muscle spindles, walk with a waddling, uncoordinated gait; they also exhibit abnormal positioning of the limbs, suggestive of impaired proprioception, and scoliosis." (PMID 37029664, 2024). "The observed difference in spine malalignment, namely C-shaped scoliosis exhibited by PValb-Cre;Piezo2f/f mice, as compared with an S-shaped scoliosis in Runx3 and Egr3 KO mice, indicates a variance in severity among genotypes." (PMID 32576830, 2020). "Recently, we showed that Runx3 KO mice, which lack proprioceptive circuitry and Egr3 KO mice, in which muscle spindles fail to form whereas GTOs are retained, develop scoliosis." (PMID 32576830, 2020). "Interestingly, whereas PValb-Cre; Piezo2f/f spines exhibited a C-shaped scoliosis, i.e. one curvature, Runx3 and Egr3 KO mice exhibited an S-shaped, two-curvature scoliosis." (PMID 32576830, 2020).
viral infection (3 papers, 2017 to 2018). "Consistent with CD2-Egr2/3−/− mice, Egr2- and Egr3-deficient T cells in the chimeras displayed impaired expansion and enhanced differentiation in response to viral infection." (PMID 28487311, 2017). "T-bet is highly expressed in Egr2- and Egr3-deficient T cells in response to viral infection, which is in direct contrast to a recent report that Egr2 is required for T-bet expression and that Egr2 deficiency leads to defects in both T cell activation and effector differentiation." (PMID 28487311, 2017). "T cells with a single defect in either Egr2 or Egr3 did not have significant changes in expansion, proliferation, activation markers, or differentiation in response to viral infection." (PMID 28487311, 2017). "Furthermore, mice with a single defect in either Egr2 or Egr3 in T cells did not have impaired responses to viral infection." (PMID 28487311, 2017).
autoimmune disease (2 papers, 2020 to 2022). A disorder resulting from loss of function or tissue destruction of an organ or multiple organs, arising from humoral or cellular immune responses of the individual to their own tissue constituents. "In addition, due to the overlapping role of EGR2 and EGR3, deletion of both EGR2 and EGR3 genes is necessary for the development of severe lupus-like autoimmune disease in B6 mice." (PMID 35784356, 2022).
Autoimmunity (2 papers, 2021 to 2024). The occurrence of an immune reaction against the organism's own cells or tissues. "EGR3 is a zinc finger transcription factor and has been studied primarily in the context of neurodevelopment, autoimmunity, inflammation, and angiogenesis." (PMID 34722264, 2021). "EGR3 is a member of a zinc finger transcription factor that plays an important role in regulating immune responses inducing also the expression of anti-inflammatory cytokines such as IL-10 and TGFB124, however the role of EGR3 in autoimmunity it is not clear yet." (PMID 39013887, 2024).
cognitive deficits (2 papers, 2012 to 2022). "Taken together, CH mediates cognitive impairment of pups through the inactivation of CaMKIV in the hippocampal neurons, which decreases the expression of EGR3 and further reduces the production of BDNF, thereby impairing the growth of dendritic spines." (PMID 36473844, 2022). "Our results demonstrate that the CaMKIV/EGR3 signal axis is responsible for regulating CH-mediated cognitive impairment, which provides a novel clue for the drug development of CH." (PMID 36473844, 2022).
colon cancer (2 papers, 2020 to 2024). "In colon cancer cell lines, EGR3 has binding sites in several genes associated with resistance to the cancer treatment drug 5-fluorouracil." (PMID 39399504, 2024). "In gastric and colon cancer cell lines, it has been shown that EGR3 has binding sites in several genes related to 5-fluorouracil resistance." (PMID 32518380, 2020).
end-stage renal disease (2 papers, 2021 to 2025). "On the other hand, among the 15-gene signature selected for day 7, only EGR3 had previously been implicated in immune functions in patients with end-stage renal disease." (PMID 40370459, 2025).
leiomyoma (2 papers, 2007). A well-circumscribed benign smooth muscle neoplasm characterized by the presence of spindle cells with cigar-shaped nuclei, interlacing fascicles, and a whorled pattern. "Leiomyomas express these and several other transcription factors that interact with TCF8 including Runx, CITED, EGR1, EGR3, E2F1, Nurr77, c-Myc, Max, and Mad, whose expression is validated in this and our previous study." (PMID 17716379, 2007). "They included several genes such as NR2F1, PNN, Smad4, Smad5, STAT5B, JUN, TGIF2, and ATF1 that were over-expressed while RUNX3, STAT1, STAT6, EGR3, GAS7, Smad1, and EDF1 were underexpressed in leiomyomas as compared to keloid/incisional scars." (PMID 17718906, 2007). "In contrast, the expression of EGR3, ECM2, THBS1, GAS1 and FBLN5 in scars and RUNX3 and COL18 expression in peritoneal adhesions was higher as compared to leiomyomas." (PMID 17718906, 2007).
lung adenocarcinoma (2 papers, 2020 to 2025). A carcinoma that arises from the lung and is characterized by the presence of malignant glandular epithelial cells. "Accordingly, EGR1, EGR2, and EGR3 were differentially expressed genes (DEGs) in several cancers, such as bladder urothelial carcinoma (BLCA), BRCA, and lung adenocarcinoma (LUAD)." (PMID 33614706, 2020).
prostate tumor (2 papers, 2013 to 2017). "EGR3 is highly expressed in some cancer, such as prostate tumors, but its role in tumorigenesis and drug resistance remains largely unknown." (PMID 29088753, 2017). "Based on our analysis of the immunohistochemical labeling intensity of Egr3 in tissue sections, we conclude that Egr3 protein is more strongly expressed in prostate tumor epithelial tissue than in normal prostate glands, which is in good agreement with the RNA expression analysis." (PMID 23342084, 2013).
scleroderma (2 papers, 2024). Scleroderma is a rare autoimmune connective tissue disorder characterized by abnormal hardening of the skin and, sometimes, other organs. "EGR3 is upregulated in the fibrotic dermis of mice with scleroderma, and increased EGR3 expression contributes to the upregulation of fibrotic genes such as ACTA2 and COL1A1." (PMID 37957540, 2024). "Notably, increased Egr3 expression promotes pro-fibrotic responses in scleroderma and leads to myofibroblast accumulation in lesional dermis." (PMID 39612288, 2024).
triple-negative breast carcinoma (2 papers, 2020 to 2025). An invasive breast carcinoma which is negative for expression of estrogen receptor (ER), progesterone receptor (PR), and human epidermal growth factor receptor 2 (HER2). "Subtype-specific evaluation revealed lowest EGR3 expression in triple-negative breast cancer (TNBC), correlating strongly with immune response signatures." (PMID 41472745, 2025). "Although little is known about the role of EN1 and EGR3 in GBM, previous work showed that EN1 is a hub gene and that its downregulation significantly reduced the viability of triple-negative breast cancer cell lines." (PMID 32612655, 2020).
acute lymphoblastic leukemia (1 paper, 2023). Leukemia with an acute onset, characterized by the presence of lymphoblasts in the bone marrow and the peripheral blood. "This study identified EGR3 as a regulator of B-lineage specification and commitment processes in the context of infant KMT2A::AFF1 acute lymphoblastic leukemia." (PMID 37100882, 2023).
acute myeloid leukemia (1 paper, 2022). Acute myeloid leukemia (AML) is a group of neoplasms arising from precursor cells committed to the myeloid cell-line differentiation. "P21 and EGr3 are intrinsic factors involved in blocking the differentiation of normal HSCs in acute myeloid leukemia due to the binding of SMAD3, an active transducer of transforming growth factor β1 (TGFβ1), to Egr3." (PMID 35806290, 2022).
basophilic leukemia (1 paper, 2021). "In the present study, RNA sequencing analysis revealed that Egr3 was one of the most highly upregulated genes in rat basophilic leukemia cells (RBL2H3) stimulated with antigen." (PMID 34234781, 2021). "Early growth response 3 gene (Egr3) was one of the most highly upregulated genes in rat basophilic leukemia (RBL2H3) cells stimulated by antigen." (PMID 34234781, 2021).
bipolar I disorder (1 paper, 2015). A bipolar disorder that is characterized by at least one manic or mixed episode. "Nominal associations were also found between two linked EGR3 SNPs, rs10104039 and rs10095121, and child bipolar I disorder in a family based association study of primarily EU participants (88% EU; p = 0.027 and p = 0.028)." (PMID 26474411, 2015).
blepharoptosis (1 paper, 2011). "Egr3-deficient mice have blepharoptosis which is a physiological sign of abnormal sympathetic innervation from the SCG neurons to the eye and a failure to properly elevate upper and lower eyelids." (PMID 21980528, 2011).
brain tumor (1 paper, 2025). "This study investigates the role of EGR3 in GBM, an aggressive and treatment-resistant brain tumor." (PMID 40649712, 2025).
cardiac hypertrophy (1 paper, 2017). "As Egr1 and Egr3, two paralogous genes of Egr2, are both CV genes, and Egr2 is likely a CV gene and an essential regulator for TAB-induced cardiac hypertrophy." (PMID 28790436, 2017).
cervical tumor (1 paper, 2017). "According to the available data in the Human Protein Atlas, most of tested cervical tumor samples were positive for protein expression of EGR3, NR4A2, SOX9, PA2G4, ENO1, and TEAD4." (PMID 28670312, 2017).
cutaneous squamous cell carcinoma (1 paper, 2021). "The microarray data revealed a decreased expression of EGR3 especially acted as a potential candidate gene for the diagnosis and prognosis of cutaneous squamous cell carcinoma." (PMID 34178038, 2021).
dysautonomia (1 paper, 2011). An acute or chronic disorder, affecting the sympathetic or parasympathetic nervous system. "However, it is not known whether dysautonomia in the absence of Egr3 is due to failure of sympathetic neurons to properly innervate target tissues, neuron death or a combination of the two processes." (PMID 21980528, 2011).
Friedreich ataxia (1 paper, 2010). An inherited condition that affects the nervous system and causes movement problems. "We also checked the mRNA expression levels of SRF, TFAP2, and EGR3 in lymphoblasts derived from an Friedreich ataxia patient (GM16214) and from a healthy control (GM16215)." (PMID 20808827, 2010).